ASXL1 (ASXL transcriptional regulator 1)
Diseases named in the same sentence as ASXL1 in open-access papers (continued):
Sharing a sentence is not in itself a finding about the gene and the disease.
leukemia (continued). "Molecules with therapeutic properties, including BRD4 and HDAC inhibitors, that reverse the action of mutant ASXL1 have been investigated, which suggests the potential treatment strategy against ASXL1-mutated leukemia." (PMID 33799787, 2021). "In MDS, ASXL1 mutations are independent adverse prognostic factors both in overall and leukemia-free survival." (PMID 34947882, 2021). "In conclusion, this meta-analysis revealed that ASXL1 mutation had a significant adverse effect on the prognosis of PMF patients, and PMF patients with ASXL1 mutations had a shorter OS and a greater possibility of transformation to leukemia." (PMID 33386934, 2021). "Taken together, these findings suggest that C-terminally truncated mutant ASXL1 proteins are highly expressed in leukemia cells and impair the association of wild-type ASXL1 with BAP1 in a dominant-negative manner." (PMID 32683582, 2021). "ASXL1 mutation is associated with some human cancer types such as leukemias and Bohring–Opitz syndrome." (PMID 34112093, 2021). "Taken together, these data support a mechanism in which a common leukemia-associated mutation, ASXL1, is linked to epigenetic upregulation of BCL2 expression and to enhanced sensitivity to VEN and AZA." (PMID 34548471, 2021). "Several NGS studies observed shorter OS or leukemia-free survival in MF patients with mutations in ASXL1, SRSF2, or EZH2." (PMID 32781570, 2020). "To further investigate the role of RUNX1 mutations to the myeloid transformation in ASXL1-mutated leukemia, we performed in vitro and in vivo expressing either ASXL1 or RUNX1 single mutant or combination of ASXL1 with RUNX1 mutant." (PMID 31640815, 2019). "Co-expression of two mutant genes increased myeloid stem cells in animal model, suggesting that cooperation of RUNX1 and ASXL1 mutations played a critical role in leukemia transformation." (PMID 31640815, 2019). "The present study demonstrated the biological and functional evidence for the critical role of RUNX1-MT in ASXL1-mutated leukemia in the pathogenesis of myeloid malignancies." (PMID 31640815, 2019). "Taken together, we found that the gain-of-function of RUNX1-MT enhanced among ASXL1-mutated leukemia in vitro and in vivo." (PMID 31640815, 2019). "Our results demonstrated that RUNX1-MT have critical roles in the leukemia transformation including augmentation of cell proliferation, blocked differentiation, and increased self-renewal activity in ASXL1-mutated cells." (PMID 31640815, 2019). "This BAP1-induced mobility shift was also observed when we used the other leukemia-associated ASXL1 mutations [(c.1934dupG; G646WfsX12 and c.1772dupA; Y591X)]." (PMID 30013160, 2018). "SETBP1-D868N is an oncogenic mutation of SETBP1, and ASXL1-MT is a leukaemia-associated ASXL1 mutant [ASXL1 (1900–1922del; E635RfsX15)]." (PMID 30367089, 2018). "We first examined the interaction between a leukemia-associated ASXL1 mutant [ASXL1 (1900–1922del; E635RfsX1517, which here we refer to as ASXL1-MT)] and BAP1 in 293T cells." (PMID 30013160, 2018). "For example, it was suggested that ASXL1 mutation was a loss-of-function mutation because of failure in detecting mutant protein in human leukemia cells." (PMID 28697759, 2017). "Our mouse model provided an ideal platform to investigate the impacts of Asxl1 mutation per se on global gene expression patterns, since the genetic backgrounds of our mice were far less complicated than those in human leukemia cells." (PMID 28697759, 2017). "Despite the somatic ASXL1 mutations frequently reported in leukemia patients, the mechanisms by which ASXL1 mutations cause cancer are not fully understood." (PMID 28701722, 2017).
leukemia (continued). "Actually, recent data have demonstrated a loss of ASXL1 protein in leukemia samples with ASXL1 mutation, indicating that these mutations are loss-of-function disease alleles." (PMID 22436456, 2012). "In leukemia, heterozygous frameshift mutations of ASXL1 are predominantly observed." (PMID 40562788, 2025). "Pharmacologic KDM6B inhibition blocks the growth of ASXL1-mutated leukemia cells." (PMID 37917239, 2024). "Additionally, transplantation assays using HSC/HPCs from this mouse model demonstrated that mutated Asxl1 accelerated the development of leukemia due to AML1-ETO9a (truncated form with enhanced leukemogenicity) expression." (PMID 36068610, 2022). "ASXL1 is frequently mutated in hematological malignancies, and its mutations have been associated with drug resistance, inferior response to treatment, and poor prognosis of patients with leukemia or MDS." (PMID 36461044, 2022). "Loss of Asxl1 and NRasG12D collaborates to promote leukemia in mice." (PMID 34944812, 2021). "A high frequency of ASXL1 mutations have been described in this leukemia." (PMID 32216059, 2020). "The contribution of RUNX1 mutations in the pathogenesis of myeloid transformation in ASXL1-mutated leukemia, however, remains unclear." (PMID 31640815, 2019). "RUNX1 mutant directly enhanced the transcriptional activity of HIF-1α and increased its target gene expression such as ID1 which could be a potential target for future therapy in ASXL1-mutated leukemia." (PMID 31640815, 2019). "Despite reports of somatic ASXL1 mutations in leukemia, the mechanism by which ASXL1 exerts effects against cancer is unknown." (PMID 30389914, 2018). "Additionally, we have demonstrated that pharmacologic inhibition of KDM6B in Asxl1-mutant HSPCs restores H3K27me3 level, normalizes leukemogenic gene expression and HSPC function, and reduces the tumor burden in mouse models of ASXL1 mutation–mediated leukemia." (PMID 37917239, 2024). "While certain mutations (e.g., DNMT3A, TET2, and ASXL1) are frequently observed in clonal hematopoiesis and seem to occur relatively early in leukemogenesis, others tend to emerge later during the progression of leukemia, they include mutations in FLT3, NRAS, and RUNX1." (PMID 37958832, 2023). "In addition, C-terminally truncated ASXL1 can be detected in leukemia cells with an ASXL1 mutation and expression of ASXL1 with a C-terminal truncation may confer a gain-of-function by promoting BAP1 activity." (PMID 33483612, 2021). "In leukemia, such as MDS/AML, chromatin dysregulation plays a critical role through mutations in key DNA and histone modifiers, for example TET2, DNMT3A, ASXL1, and EZH2, which are frequently mutated in MDS/AML." (PMID 40562788, 2025). "In this way, ASXL1 mutation contributes to the upregulation of PRDM16, higher levels of which are associated with lower survival rates in leukemia patients." (PMID 40562788, 2025). "Leukemias harboring loss-of-function mutations in Polycomb-group epigenetic regulators, such as EZH2 and ASXL1, are associated with poor clinical outcomes and remain a major therapeutic challenge." (PMID 40561338, 2025). "As a result, the mutant ASXL1 is expressed at a level surpassing that of WT ASXL1 in leukemia, indicating a dominant-negative effect of the mutant." (PMID 40562788, 2025). "*BAP1deubiquitinates the cell cycle regulator HCF‐1 and its binding partner OGT1 to suppress proliferation and cell cycle progression, limiting myeloid transformation. *Mutant ASXL1‐MT/BAP1 complex promotes leukaemia transformation." (PMID 39108012, 2024). "TET2, ASXL1, DNMT3A, and SF3B1 are all known to harbor causal leukemia variants, and somatic variants in SRSF2 have been described in myelodysplastic syndrome." (PMID 39132489, 2024). "In particular, considering the frequent mutations of ASXL1 in various types of leukemia, the synergistic role of ASXL2 and PRC2 complex in leukemia development and hematopoiesis has been explored." (PMID 38791157, 2024).
leukemia (continued). "According to previous literature studies, SH2B3 and ASXL1 mutations are associated with poor prognosis of MPN patients, such as low overall survival (OS), progression of MF and leukemia transformation." (PMID 38618943, 2024). "So far ASXL1, SRSF2, IDH2 have been identified as unfavourable risk factors affecting overall (OS), leukemia-free (LFS), or myelofibrosis-free survival (MFFS) in PV." (PMID 36242602, 2023). "NRAS and also ASXL1, RUNX1, and SETBP1 gene mutations were proved to be independent risk factors for inferior OS and the increased risk of MDS progression to leukemia." (PMID 36982819, 2023). "Recently, it was suggested that SF3B1, SRSF2, ASXL1, TET2, and DNMT3A gene mutations contribute to the risk of MDS evolution to leukemia and also influence therapy response and overall survival." (PMID 36982819, 2023). "In leukaemia the gain-of-function of ASXL1 mutants increase PR-DUB activity; the stabilization of BAP1 and its undue ASXL1 mutant-dependent chromatin recruitment leads to aberrant oncogenic pattern of gene expression." (PMID 36318367, 2022). "It was found that the mutant ASXL1 protein with c-terminal truncation was expressed at a much higher level in ASXL1 heterozygous leukemia cells than the wild-type protein and lost its ability to interact with FoxK1/2." (PMID 35903069, 2022). "The UBASH3A, SF3B1, RUNX1 and ASXL1 mutations gradually appeared and became the major clones at MDS stage, while IDH2 gradually emerged as the dominant clone at leukemia stage." (PMID 36167633, 2022). "They further evaluated the impact of deleting endogenous mutant ASXL1 (C-terminal-truncated) in a background of additional oncogenic alterations using leukemia cell lines (i.e., K562 and Kasumi cells)." (PMID 36068610, 2022). "Our previous studies have shown that leukemia-specific C-terminus truncated ASXL1 is able to stabilize BAP1 and enhance BAP1’s recruitment to chromatin which promotes the expression of a pro-leukemic transcriptional signature." (PMID 36180891, 2022). "The clonal evolution analysis of FA case (P1001) showed the mutations of UBASH3A, SF3B1, RUNX1 and ASXL1 gradually appeared at the later stage of MDS, while the IDH2 alteration become the dominant clone at the leukemia stage." (PMID 36167633, 2022). "We show that the C-terminally truncated mutant ASXL1 proteins are expressed at much higher levels than the wild-type protein in ASXL1 heterozygous leukemia cells, and lose the ability to interact with FOXK1/K2." (PMID 32683582, 2021). "ASXL1 mutations alter the epigenome of hematopoietic stem cells (HSC) and increase the susceptibility to leukemia transformation." (PMID 33386934, 2021). "Such displacement is dependent on BAP1 catalytic activity, in agreement with the requirement of ASXL1 for correct PRC2 activity at the HOX genes in leukemia." (PMID 34186021, 2021). "ASXL1 gene mutation was associated with IPSS intermediate risk, increased blasts, short survival, and significantly shortened transformation time to leukemia." (PMID 33178287, 2020). "In PV, ASXL1 and SRSF2 were associated with inferior OS, SRSF2 and IDH2 with shorter leukemia-free survival and SRSF2 with shorter myelofibrosis-free survival." (PMID 32781570, 2020). "From clonal hematopoiesis to secondary leukemia of MDS, both TET2 and ASXL1 gene mutations are common in MDS and secondary leukemia patients." (PMID 33178287, 2020). "Several studies have provided evidence for the adverse impact of somatic mutations in ASXL1, EZH2, IDH1/2, and SRSF2 on shorter OS or leukemia-free survival in patients with PMF." (PMID 32781570, 2020).
leukemia (continued). "Conditional deletion of Asxl1 in murine hematopoietic progenitors resulted in progressive anemia and leukemia with multilineage dysplasia similar to human myelodysplastic syndrome (MDS), but without evidence of MF31." (PMID 31511492, 2019). "To evaluate if Id1 overexpression correlates with the development of leukemia in mice, we examined Id1 expression in the spleen, liver, and BM of mice induced by ASXL1-R693X, RUNX1-R135T, and combination of ASXL1 and RUNX1 mutants as well as control." (PMID 31640815, 2019). "Bap1 depletion resulted in a profound reduction in the numbers and sizes of cSAM cell colonies, and also delayed the development of leukemia in mice, suggesting an important role for Bap1 in ASXL1-MT-induced leukaemogenesis." (PMID 30013160, 2018). "We then assessed the effect of coexpression of BAP1 and ASXL1-MT on the leukaemogenicity of RUNX1-ETO leukemia." (PMID 30013160, 2018). "In leukemia, the CRISPR/Cas9 system was used to correct somatic mutations in the ASXL1 gene." (PMID 39955067, 2025). "Further research into the mono-ubiquitination of ASXL1 and its role in tumorigenesis is essential for a better understanding of leukemia development and could lead to new targeted therapies." (PMID 40562788, 2025). "To examine whether similar findings in our mouse models can also be translated to human leukemia, we examined the TE expression profile of samples from patients with MDS carrying ASXL1/EZH2 mutations." (PMID 40561338, 2025). "The relationship between ASXL3 and tumor development is unclear, as it is rarely mutated and not as closely associated with leukemia as ASXL1 and ASXL2." (PMID 38791157, 2024). "Genetic depletion of BAP1 or inhibition of BAP1 activity by small molecule inhibitors could dramatically reduce the tumor growth of BAP1-dependent cancer, such as ASXL1-mutant leukemia, breast cancer, and SCLC." (PMID 36180891, 2022). "Interestingly, the vast majority of ASXL1 peaks are localized at promoters, which is consistent with our previous studies in leukemia and breast cancer cells." (PMID 36180891, 2022). "Notably the expression of C-terminal truncation of ASXL1 has been observed in a few leukemia cell lines." (PMID 33796551, 2021). "Finally, we examined the functional consequence of deleting the C-terminally truncated ASXL1 mutant on leukemia cell growth." (PMID 32683582, 2021). "Notably, the protein expression of C-terminally truncated mutant ASXL1 was much higher than that of full-length ASXL1 in both types of leukemia cells." (PMID 32683582, 2021). "Clonal hematopoiesis of indeterminate potential (CHIP) in leukemia associated genes including DNMT3A, ASXL1, TET2 with a variant allele frequency (VAF) of ≥2% can confer a predisposition for hematological malignancy including overt leukemia, as well as thrombosis, stroke and cardiovascular events." (PMID 34639121, 2021). "Given the promising results in murine leukemia models with co-occurring mutations, we then evaluated the ex vivo activity of TP-0903 and TKIs in human primary samples with coexisting recurrent mutations (e.g., FLT3-ITD, IDH1/2, ASXL1, DNMT3A, NPM1, and SRSF2)." (PMID 33268594, 2020). "CHIP is driven by somatic mutations in leukaemia driver genes, such as Janus Kinase 2 (JAK2), Tet methylcytosine dioxygenase 2 (TET2), ASXL Transcriptional Regulator 1 (ASXL1) and DNA (cytosine-5)-methyltransferase 3A (DNMT3A), leading to reduced diversity of the blood pool." (PMID 32526214, 2020). "Our results of reduction of ID1 expression by the inhibition of HIF-1α in transformed leukemia cells supports that ID1 is controlled by HIF-1α, which might be deregulated by either ASXL1 or RUNX1 mutation or coexisted mutant of both genes." (PMID 31640815, 2019). "Data presented here showed that either ASXL1-R693X or RUNX1-R135T mutant alone did not have much effect on leukemia cells; however, cooperative mutations led to the enhancement of HIF-1α recruitments to the promoter region of the ID1 gene." (PMID 31640815, 2019).
leukemia (continued). "Next, we assessed the role of ASXL1-MT in RUNX1-ETO leukemia using a human cell-based assay." (PMID 30013160, 2018). "In our model, Asxl1 G643WfsX12 mutation did not lead to leukemia or other blood malignancies in a 18-24-month observation period, indicating that a physiological dose of Asxl1 G643WfsX12 was not sufficient for leukemogenesis." (PMID 28697759, 2017). "In recent years, a large number of clinical studies on the impact of ASXL1 mutations in PMF have been reported, some of which have revealed that ASXL1 mutations may be related to the prognosis of PMF and leukemia transformation, but its exact role remains controversial." (PMID 33386934, 2021). "According to the 2022 European leukemia network (ELN) guidelines, ASXL1 is categorized as AML with myelodysplasia‐related genes." (PMID 38146893, 2023). "Another study found that loss of SETD2 led to down-regulated expression of the tumor suppressor ASXL1 (Additional Sex Combs-Like protein 1) and an upregulation of ERG, resulting in accelerated leukemia development." (PMID 30818762, 2019). "Coexpression of ASXL1-MT and BAP1 promoted RUNX1-ETO9a-induced leukemia progression with higher efficiencies than did ASXL1-MT alone." (PMID 30013160, 2018). "KRAS is considered relevant in leukemia formation; the enrichment in KRAS gene set confers the possibility that mutant ASXL1 act as a cofactor in disease development." (PMID 28697759, 2017). "Furthermore, in mutant ASXL1-driven leukemia models, reducing BAP1’s catalytic activity has been shown to inhibit leukemia development and extend the survivability of animals." (PMID 35194152, 2022). "One possible mechanism is the truncated ASXL1 could interact with BRD4, leading to the openness of chromatin in leukemia cells." (PMID 32669118, 2020). "Similarly, PMA-induced monocytic differentiation of U937 cells, a human leukemia monocyte cell line, was also attenuated by the combined expression of RUNX1-R135T with ASXL1-R693X compared to single mutant." (PMID 31640815, 2019). "To compare our mouse model with human disease, we profiled gene expression of leukemia cells from a total of 343 AML patients and compared the expression patterns between samples with (N = 50) and without (N = 293) ASXL1 mutation." (PMID 28697759, 2017). "In addition, we found that GSK-J4 treatment led to significantly prolonged survival and reduced leukemia burden in mice xenografted with AML patient-derived xenograft (PDX) #1 cells (ASXL1 G646WfsX12) without reducing body weight." (PMID 37917239, 2024). "For example, in vivo deletion of Asxl1 was shown to result in subtle phenotypes including defects in the frequencies of myeloid and lymphoid cells in blood, marrow or other hematopoietic organs in mice but not myelodysplastic syndrome (MDS) or leukemia." (PMID 28697759, 2017).